EGFR (epidermal growth factor receptor)
Diseases named in the same sentence as EGFR in open-access papers (continued):
Sharing a sentence is not in itself a finding about the gene and the disease.
tumor (continued). "To monitor the tracheal branches that are associated with the tumorous discs, we induced the EGFR-Pcn tumor and labelled the trachea with membrane tethered GFP (with LHG lexO-CD2:GFP, a tracheal-specific driver)." (PMID 31568500, 2019). "Real time molecular imaging using fluorescent erlotinib is able to identify ex vivo tumours with EGFR mutations." (PMID 30612556, 2019). "Previous studies have shown that the combination of CDKN2B loss and EGFR amplification are early evolutionary events in GBM as they can be observed as a joint event in all parts of the tumor." (PMID 31842352, 2019). "Mutations disrupt the normal functioning of EGFR/ERK signalling which increases the growth rate of the tumour." (PMID 31016574, 2019). "The analysis of single nucleotide variants in KRAS, NRAS, PIK3CA, BRAF, and EGFR using cfDNA has been shown to have >80% concordance when compared to tumor tissue of colorectal, lung, and breast cancer patients." (PMID 30364656, 2018). "Increased expression of EGFR in the primary tumor is associated with unregulated proliferation, malignant transformation, metastasis and resistance to apoptosis of cancer cells." (PMID 30445978, 2018). "Therapeutic resistance to EGFR inhibitors can result from intrinsic compensatory mechanisms such as KRAS mutations or from acquired resistance due to tumor heterogeneity and/or receptor cross-talk and heterodimerization." (PMID 30044378, 2018). "Benefit was primarily shown in those with EGFR mutation-positive disease; however, tumor samples were available in only 53% of the intent-to-treat population." (PMID 30088048, 2018). "Previous studies into the detection of EGFR mutations using plasma cfDNA have noted low sensitivity compared with tumor tissue biopsies with an average sensitivity of 65–70% and high specificity (> 88%)." (PMID 30526536, 2018). "The mutation-detecting Sanger sequencing method has been established as the ‘gold standard’ for EGFR mutation testing, but the requirement of high-quality tumor samples and the longer turnaround time limit its utility." (PMID 29623586, 2018). "We chose heterogeneous endoribonuclease-prepared siRNA pools (esiRNAs) against the frequently mutated genes PIK3CA and KRAS and coupled them to the anti-EGFR antibody cetuximab, which was internalized specifically into the tumor cells." (PMID 30001368, 2018). "Across all tumors, these data support an association between EGFR amplification and fast migratory behavior of cells, which contributes to overall tumor invasiveness." (PMID 30573757, 2018). "In conclusion, both main tumor resection and postoperative EGFR-TKI therapy were associated with better survival in pulmonary adenocarcinoma patients with unexpected pleural spread noted during thoracic surgery." (PMID 29435191, 2018). "When the cobas EGFR test yielded a result of ‘mutation not detected’ (MND), even though the C/N ratio was over 10%, the EGFR mutation was re-analyzed after increasing the tumor ratio by macrodissection." (PMID 29323170, 2018). "After adjusting possible confounders, including age, smoking, stage, and tumor size, EGFR mutation was one of the predictors for subsequent BM (HR = 1.89, 95% CI = 1.12~3.17, p = 0.017)." (PMID 29447182, 2018). "Encouragingly, ctDNA(circulating cell-free tumor DNA) provide a high degree of specificity to detect EGFR mutations compared to tissue DNA." (PMID 30383772, 2018). "A tumor biopsy specimen tested positive for the EGFR L858R mutation, so the patient was treated with erlotinib." (PMID 29764505, 2018). "EGFR staining was associated with higher tumor stage and grade, and its intensity correlated with metastatic disease in the univariate but not multivariate analysis." (PMID 29135410, 2018). "Literature review revealed association of EGFR expression with high tumor grade, stage, tumor progression and poor clinical outcome." (PMID 29879970, 2018).
tumor (continued). "One limitation for EGFR mutation testing is the scarcity of tumor tissue in patients with advanced disease." (PMID 29930751, 2018). "It is known that gefitinib inhibits the epidermal growth factor receptor (EGFR), and is now indicated for the first-line treatment of patients with NSCLC whose tumours have specific EGFR mutations." (PMID 29726967, 2018). "Strikingly, deletion of EGFR exon 19 and a point mutation in exon 21 account for up to 90% of EGFR mutations in the clinic and correspond to two distinct tumour subtypes with different clinical characteristics and response to EGFR tyrosine kinase inhibitors." (PMID 29849818, 2018). "A large body of randomised clinical trials demonstrated the superior clinical effectiveness of EGFR TKIs compared with standard chemotherapy in patients with stage IIIB or IV NSCLC whose tumours tested positive for EGFR mutations." (PMID 29382302, 2018). "Retrospective findings from clinical studies, supported by a biological rationale, have suggested a potential clinical interest for some molecular alterations which seem to negatively affect tumor susceptibility to EGFR inhibition." (PMID 30081606, 2018). "Six of the 12 patients had tumor size reductions; three achieved durable stable disease, including one with EGFR exon 19 and T790M mutations." (PMID 29973561, 2018). "Patients with wild type primary tumor were tested for all mutations, except for the EGFR p.T790M one, because this latter is usually induced by EGFR-inhibitors, not used in these patients." (PMID 30110953, 2018). "Both AURKA and AURKB are implicated in tumour resistance pathways for selective EGFR inhibitors in cancer." (PMID 29115879, 2018). "All together, our data show the in vivo anti‐tumor activity of Orlistat as a single agent against the clinically relevant TKI‐resistant EGFR T790M/L858R mutation." (PMID 29449326, 2018). "Despite technical advances, variable concordance rates, sensitivity and specificity between blood-based and tumor samples for EGFR mutation detection have been reported, as shown in the global ASSESS study." (PMID 29623586, 2018). "For the NSCLC group, the univariate logistic regression analysis showed that sex, smoking status, histology, pSUVmax, tumor size, nodal involvement, distant metastasis, and tumor stage were significantly correlated with EGFR mutations." (PMID 29164298, 2018). "The detection of EGFR mutations by circulating tumor (ct) DNA has recently emerged as a valid and non-invasive alternative approach, overall showing a high concordance with the standard tissue genotyping." (PMID 30190486, 2018). "It has also been reported that mTOR is associated with EGFR resistance, blocking mTOR pathway can interfere with tumor growth." (PMID 29455664, 2018). "Many studies have shown that overexpression of EGFR is associated with tumor invasion, metastasis, and relapse in multiple types of cancers." (PMID 29455656, 2018). "The authors showed that modulation of ERK-dependent Bim and Mcl-1 degradation are critical for anti-tumor activity in NSCLC harboring EGFR-activating mutations." (PMID 29641535, 2018). "Overall, the in vivo data supports our in vitro findings and suggests that tumor persistence after short EGFR TKI exposure is associated with induction of Notch3 and β-catenin." (PMID 30097569, 2018). "Radiomic features from CT or PET are widely being explored by recent studies for their correlation with prognosis, treatment response or tumor phenotype including EGFR-mutation status in NSCLC patients." (PMID 29895834, 2018). "LUAD is characterized by a high frequency of tumor‐driving mutations in gene for epidermal growth factor receptor (EGFR) (10–30%) or KRAS (20–40%)." (PMID 30220105, 2018). "Based upon our current data, we have designed the immune checkpoint inhibitor expressing EGFR-CAR T regimen to overcome the concerns caused by tumor microenvironment, which leads us to an imminent phase I clinical trial (NCT03030001)." (PMID 29415996, 2018).
tumor (continued). "Dysregulation of the EGFR signalling pathway has previously been linked to tumour aggressiveness and reduced patient survival in various cancers including those of the breast and lung." (PMID 30018740, 2018). "Here, we report that the expression of Sal-like protein 4 (SALL4), was significantly higher in EGFR mutated lung tumors than in non-tumor tissue." (PMID 29691367, 2018). "Patients harbouring tumours with a PIK3CA mutation or PTEN loss were excluded specifically because data suggest the PI3K/AKT pathway is a resistance mechanism to EGFR inhibition." (PMID 29254887, 2018). "The use of NGS would likely allow to overcome the two main causes of EGFR mutation status discordance between tissue and plasma analysis, such as the intra-tumor heterogeneity and the low sensitivity of the standard diagnostic techniques." (PMID 30190486, 2018). "EGFRvIII is a mutated form of the epidermal growth factor receptor (EGFR), resulting from a tumor-specific in-frame deletion creating a constitutively active surface receptor protein." (PMID 30386740, 2018). "In agreement with our findings on the LUAD caused by the EGFR tumor‐driving mutation, HCI‐2509 treatment of C57BL/6N(KRAS G12V) mice resulted a significant increase of H3K4me2 levels, whereas H3K9me2 levels were unaffected." (PMID 30220105, 2018). "Approximately about 10% of patients with Non-small cell lungcancer (NSCLC) in the US and about 35% in East Asia have tumor associated EGFR." (PMID 30108422, 2018). "The results of the current study are in line with that previous data in that low mRNA levels of EGFR or HIF-1α mRNA are associated with poor tumor-specific survival." (PMID 30513863, 2018). "In our study, tumour tissue from bronchial biopsy was the most frequently used source of tumour material for EGFR mutation analysis (70.0%) while cytology specimens were used in about one third of patients at the time when the study was carried out." (PMID 29382302, 2018). "EGFR mutation detection was performed successfully in 96.5% of the 363 R-EBUS-guided brushing specimens that contained tumor cells." (PMID 29643378, 2018). "Downregulated MUC4 has been reported to induce tumor progression in conjunction with an EGFR mutation." (PMID 30404194, 2018). "Mutation testing was mainly performed on biopsy tumour tissue specimens (69.0%) using a qPCR-based test (90%) (47.0% Therascreen EGFR PCR Kit)." (PMID 29382302, 2018). "Earlier studies observed the PKI 166, epidermal growth factor receptor (EGFR) inhibitor attenuated EGFR activation in tumour associated endothelial cells and caused cell apoptosis." (PMID 29455663, 2018). "Of note, patients with low levels of EGFR‐activating mutation allele fractions had reduced tumour burden (median 17 mm) by RECIST measurements, as compared to those with intermediate (median 42 mm) and high (median 80 mm) levels of EGFR‐activating mutation." (PMID 29848757, 2018). "Data from clinical trials have suggested allele-specific real-time polymerase chain reaction assays that would be capable of detecting EGFR T790M mutations with as few as 5% tumor cells." (PMID 29914100, 2018). "Subsequently, another biopsy sample of the tumor tested positive for EGFR L858R and T790M mutations, so the patient was treated with osimertinib, and his disease was stabilized for 13 months." (PMID 29764505, 2018). "45.2% of our cases revealed EGFR over-expression, and significant association of EGFR was noted with tumor stage and disease-free survival, which are among the most important prognostic factors in head and neck SCC." (PMID 29954411, 2018). "Positive mutations of the EGFR gene were identified in 15.1 and 11.0% of the tumor and plasma samples, respectively." (PMID 29623586, 2018). "Increased relative cerebral blood volume and cerebral blood flow within enhancing tumor were associated with EGFR amplification and CDKN2A loss." (PMID 29459844, 2018).
tumor (continued). "This pooled analysis aims at evaluating the diagnostic accuracy of circulating tumor (ct) DNA for the detection of EGFR-T790M mutation in NSCLC patients who progressed after EGFR-TKIs." (PMID 30190486, 2018). "Our results suggest the need to perform mutational analysis in all available tumor samples of patients before deciding to commence anti-EGFR treatment." (PMID 30344942, 2018). "Multivariate analysis showed main tumor resection and EGFR-TKI therapy were associated with better survival." (PMID 29435191, 2018). "C797S mutation had been identified in cis or in trans with T790M mutation in tumor specimens from patients who experienced treatment failure with third-generation EGFR-TKIs." (PMID 29713646, 2018). "78% of 97 advanced-stage (IIIB, IV) NSCLCs featuring an EGFR variant in the primary had the same mutations in ctDNA; EGFR(p.L858R) in either tumor tissue or cfDNA predicted shorter OS and PFS." (PMID 29441349, 2018). "Such “liquid biopsies” have been effective in lung neoplasia e.g., for monitoring treatment responses to EGFR inhibitors through identification of mutation T790M in EGFR in circulating tumor DNA." (PMID 29467960, 2018). "Following approval by the FDA, the COBAS EGFR mutation test v2 (Roche) became the new proposed paradigm of treatment guidelines for EGFR T790M by testing cfDNA prior to tumor tissue, and has been applied in clinical practice." (PMID 30444875, 2018). "Collectively, these results suggested that knockdown of SALL4 enhances the sensitivity of EGFR mutation-positive tumor cells to Erlotinib in vivo." (PMID 29691367, 2018). "(1.055–8.221)] and more likely to have EGFR mutation-positive tumors (71% of the EGFR-positive tumours were found in women vs 46%of the EGFR-negative tumours)." (PMID 30235778, 2018). "High expression of EGFR (evaluated by IHC in tumor tissues) is associated with a large tumor size, tumor necrosis, high mitotic index, the histological grade of tumor malignancy and a poor clinical stage." (PMID 30373614, 2018). "The T790 M and L858R mutations, concomitantly detected in two cases, were the only EGFR variants found simultaneously in the same tumor sample." (PMID 29368620, 2018). "Defective MVB sorting of EGFR and other growth factor receptors is linked to tumour formation and common diseases." (PMID 30190330, 2018). "For example, approximately 10% of patients with NSCLC in the US have tumor involving the epidermal growth factor receptor (EGFR) somatic activating mutations." (PMID 29562902, 2018). "Taken together, these studies highlight the importance of sialic acid in EGFR signaling, however there are some caveats associated with manipulating the global sialylation of tumor cells." (PMID 29402301, 2018). "On one hand, it is known that EGFR overexpression in BC is associated with increased tumour size and worse patient outcomes and negatively correlates with ER status, explaining the observed negative association with MED7." (PMID 29588513, 2018). "Tumor growth measurements, histological and immunohistochemistry analysis, Western blotting, EGFR and K-RAS mutation detection and gefitinib sensitive assay were performed to evaluate the characteristic of established PDX models." (PMID 29788985, 2018). "For 45 of 50 patients, EGFR mutations were detected before treatment in tumour and/or plasma and more than one plasma sample was available from clinical follow‐up." (PMID 29848757, 2018). "Data were collected from the Spanish cohort of patients in the large, non-interventional, diagnostic ASSESS study (NCT01785888) evaluating the utility of circulating free tumor-derived DNA from plasma for EGFR mutation testing." (PMID 29623586, 2018). "Recently, we described the modular UniCAR platform technology for retargeting of T cells to various tumor-associated surface antigens (TAAs) including EGFR that meets this criterion." (PMID 29876011, 2018).
tumor (continued). "After adjusting possible confounders, including age, smoking, stage, and tumor size, EGFR mutation became one of the predictors for subsequent BM (HR = 1.89, 95% CI = 1.12~3.17, p = 0.017)." (PMID 29447182, 2018). "Plasma circulating tumor DNA (ctDNA) is an ideal approach to detecting the epidermal growth factor receptor (EGFR) T790M mutation, which is a major mechanism of resistance to first-generation EGFR-tyrosine kinase inhibitor (TKI) therapy." (PMID 29789021, 2018). "Among patients with carcinoembryonic antigen levels < 2.12 ng/mL, EGFR mutations were associated with age (P < 0.001), tumour size (P < 0.001), histology (P < 0.001), and stage (P < 0.001)." (PMID 29849818, 2018). "Vascular endothelial growth factor-A (VEGF-A) production and tumor vessel formation were found to be more significantly enriched in ALK-rearrangement NSCLC than that in epidermal growth factor receptor or Kirsten rat sarcoma viral oncogene mutated NSCLC." (PMID 29318404, 2018). "For instance, EGFR mutations across different TCGA tumor types exhibit a 0.23 < GScore < 0.82 while mutations in KRAS have GScore values in the range of 0.36–0.97." (PMID 29848362, 2018). "Previous reports showed that the EGFR and AurkA protein levels were elevated in tumor tissue, which represents a risk group with a poor disease-free survival." (PMID 30308958, 2018). "For example, deficient signalling of the EGFR and other receptor tyrosine kinases is associated with human diseases such as Alzheimer’s, while EGFR overexpression is associated with the development of a variety of tumours." (PMID 29860480, 2018). "We developed a 6-color digital PCR assay for the detection and quantification of 19 most prevalent EGFR sensitizing and resistance mutations and evaluated this assay on 82 tumor and plasma samples from NSLC patients." (PMID 30647840, 2018). "A bispecific FP containing CD19 linked to anti-Her2 and anti-EGFR scFv was very potent against tumor cells expressing both antigens (IC50=0.75 pM)." (PMID 30400835, 2018). "Overexpression or aberrant activation of EGFR has been demonstrated to cause tumor growth and progression of NSCLC." (PMID 29570930, 2018). "Currently, tumor tissue is usually employed for the identification of activating as well as T790M resistance EGFR mutations." (PMID 29719623, 2018). "Overexpression or enhanced activation of ADAM17 in tumor cells has been linked to cancer initiation and progression, mostly via EGFR activation." (PMID 29662625, 2018). "In total, 84 (27.4%) samples had original EGFR activating mutations (19del, L858R and other rare mutations) that had been detected in primary tumor specimens before TKI administration, whereas 128 (41.7%) samples exhibited wild-type EGFR." (PMID 29789021, 2018). "We detected EGFR mutations in 15.1% of the aNSCLC patients according to tumor samples and in 11.0% according to plasma ctDNA." (PMID 29623586, 2018). "EGFR/EpCAM subgroups of patients were tested for associations with the clinical parameters tumor localization, grading, T stage, N stage, age, and p16 status, which is a surrogate marker for HPV infection." (PMID 30261040, 2018). "Although EGFR mutation testing was mainly performed in patients with adenocarcinoma, other histological tumor types cannot be excluded." (PMID 29587656, 2018). "We tested the BetA effect on tumor cells transduced with mutated EGFR gene (resistant) and its sensitive parental cell line." (PMID 29867487, 2018). "The types of EGFR mutations identified in plasma and tumour (EGFR activating, resistance‐conferring mutations in EGFR and other mutations) were identical for 11 of 12 (92%) mutations before treatment, and for 9 of 12 (75%) mutations after treatment." (PMID 29848757, 2018). "In the remaining seven patients, two were found to be EGFR wild‐type in both tumour and plasma, and the remaining five have EGFR mutations detected in plasma." (PMID 29848757, 2018).